GLI1 (GLI family zinc finger 1)
Diseases named in the same sentence as GLI1 in open-access papers (continued):
Sharing a sentence is not in itself a finding about the gene and the disease.
melanoma (continued). "Additionally, the investigators observed that targeting the Hh transcription factors GLI1 and GLI2 restored the sensitivity of human melanoma cells resistant to vemurafenib and even inhibited acquired chemotherapy resistance in melanoma patients." (PMID 39611156, 2024). "We have previously demonstrated that melanoma migration and invasion can be impaired by siRNA targeting Hh pathway components: siRNA treatment targeting SMO and GLI1 was effective and proved to reduce migration and invasion in two different melanoma cell lines, SK-MEL-28 and A375." (PMID 38399442, 2024). "The finding that the blockade of CX3CL1 reverts the increase in PMN-MDSC proliferation and invasion induced by GLI1, suggests that this phenotype could be mediated by increased expression and secretion of CX3CL1 by melanoma cells." (PMID 39090759, 2024). "We then performed a migration and invasion assay on two melanoma cell lines (SK-MEL-28 and A375) where Smoothened, the upstream protein involved in Hh regulation, and GLI1, the main transcription factor that determines Hh pathway activation, were chemically inhibited." (PMID 38399442, 2024). "Notably, we observed strong significant correlations between SHH and Gli1 (p < 0.0001) and between SHH and Gli2 (p < 0.0001) in the immunohistochemical-staining melanoma samples." (PMID 37240209, 2023). "In melanoma, LDE225 decreases the tumor size with a decrease of GLI1 expression." (PMID 34642915, 2022). "To test whether a similar interaction is present in melanoma cells, we next determined whether CAXII expression was affected by SMO or GLI1 in both the SK-MEL-28 and A375 cell lines." (PMID 36230699, 2022). "Here, we identify a novel SOX2-BRD4 transcriptional complex driving the expression of GLI1, the final effector of the HH/GLI pathway, providing a novel mechanism of non-canonical SMO-independent activation of HH/GLI signaling in melanoma." (PMID 33958721, 2021). "Importantly, ectopic expression of GLI1 rescued the effect of MRT-92 and MZ1 combination in reducing melanoma cell viability." (PMID 33958721, 2021). "In this study, we identify a novel BRD4-SOX2 transcriptional complex responsible for non-canonical activation of GLI1 in melanoma." (PMID 33958721, 2021). "Further investigation revealed that TGF-β1/SMAD3 was directly involved in the noncanonical regulation of GLI1/2 activation in vemurafenib-resistant melanoma cell lines." (PMID 34572373, 2021). "Furthermore, protein levels of GLI1, SOX2, ST3GAL1, and AXL were analyzed in short-term cultures of primary and metastatic melanomas." (PMID 33203881, 2020). "In the melanoma animal model, treatment with LDE225 inhibited GLI1 expression." (PMID 33396427, 2020). "In addition, we illustrated that circ-GLI1 activated Hedgehog/GLI1 and Wnt/β-catenin pathways to induce MYC-regulated transactivation of Cyr61 in melanoma." (PMID 32732916, 2020). "In conclusion, our research unveiled that circ-GLI1 interacted with p70S6K2 to boost GLI1 and β-catenin proteins, so as to activate Hedgehog/GLI1 and Wnt/β-catenin pathways and therefore enhance MYC-activated Cyr61 expression, leading to accelerated metastasis in melanoma." (PMID 32732916, 2020). "Besides SOX2, the GLI transcription factors GLI1 and GLI2 have been suggested to be involved in melanoma progression and metastasis and to be responsible for maintenance of melanoma-initiating cells." (PMID 33203881, 2020). "Intriguingly, reports also revealed that MYC could conversely modulate GLI1 transcription, suggesting a feedback loop of MYC-GLI1 in melanoma." (PMID 32732916, 2020). "Interestingly, both Compounds 1 and 2 were shown to suppress melanoma cell proliferation with nanomolar IC50 concentrations and to reduce the expression of endogenous GLI1 protein in a dose-dependent manner." (PMID 30558232, 2018).
melanoma (continued). "In a melanoma xenograft mouse model, MRT-92 suppressed tumor growth at a systemic dose of 15 mg/Kg and significantly decreased GLI1 expression in tumor lesions, demonstrating efficient inhibition of HH signaling in vivo and providing the first evidence of anticancer therapeutic efficacy." (PMID 30558232, 2018). "While silencing GLI1 and GLI2 has recently been demonstrated to induce senescence to restore chemosensitivity in melanoma cells, Hh signaling has not yet been linked to senescence in GBM." (PMID 29930746, 2018). "Similarly to PDGFRα inhibition, inhibition of Gli1 activation by the novel clinically available Shh inhibitor (Shh-I) LDE225 restored (P<0.05) and increased (P<0.05) melanoma cells' sensitivity to BRAF-I." (PMID 24732172, 2014). "Further, GLI1 and/or GLI2 are oncogenes, and are constitutively activated in many types of human cancers including epithelial cancers of the GI tract, brain tumors, melanoma, pediatric solid tumors, liver, lung, breast, pancreatic and prostate cancers." (PMID 24962990, 2014). "Effects of iRF on melanoma cells (B16F10 cells) are, at least in part, correlated with inhibition of HH signaling, as evident by the decreased the expression of key players in HH pathway signaling such as GLI1 and PTCH-1 and the increase of SUFU expression." (PMID 23342114, 2013). "It suppresses the epithelial-mesenchymal transition through the SHH-GLI family zinc finger 1 (GLI1) pathway in hepatocellular carcinoma and through downregulation of the methylcrotonyl-CoA carboxylase subunit 1 (MCCC1) expression in malignant melanoma and gastric cancer." (PMID 40787625, 2025). "Indeed, our data showed that chemical targeting of SMO and GLI1 can impair CAXII expression and melanoma migration and invasion, highlighting, in this experimental model, the possibility to develop small molecules that are more effective in reducing melanoma aggressiveness." (PMID 38399442, 2024). "However, the direct effects of GANT61 on SHH, Gli1, and Gli2 expressions in melanoma cells were not evident, showing no significant change unlike the results of the in vivo analysis." (PMID 37240209, 2023). "Furthermore, comparison of GLI1 and SOX2 expression levels in 477 TCGA melanoma patients showed a co-expression of these two transcripts (p < 0.0001) and a significant decrease in overall survival in cases with high expression of both SOX2 and GLI1 (p = 0.0213)." (PMID 33958721, 2021). "Treatment of melanoma cells with AKT1 inhibitors decreased the number of cells with nuclear Gli1 labeling, while increasing the number of cells with cytoplasmic Gli1 labeling, suggesting that AKT1 may be required for Gli1 nuclear localization and transcriptional activity." (PMID 26512695, 2015). "Moreover, others showed that oncogenic RAS-induced melanomas in transgenic mice express GLI1 and require SHH-GLI signaling in vitro and in vivo and that endogenous RAS-MEK and AKT signaling regulates the nuclear localization and transcriptional activity of GLI1 in melanoma." (PMID 23935925, 2013). "Targeting GLI1 and GLI2 transcription factors with GANT-61 restored sensitivity to vemurafenib-resistant cells, additionally confirming the importance of the non-canonical interplay between HH-GLI and RAS/RAF/ERK in melanoma." (PMID 37239024, 2023). "In melanoma cells, SOX2 activates GLI1 in a non-canonical SMO-independent way by binding to the CTTGGATT sequence at -423 bp upstream of the TSS and activating GLI1 expression." (PMID 37149646, 2023). "Silencing of BRD4, as well as its pharmacological depletion with MZ1 or catalytic inhibition through JQ1, prevented SOX2-binding to GLI1 promoter, without altering SOX2 expression in melanoma cells." (PMID 33958721, 2021). "Compounds 1 and 2 appear to be specific toward the HH pathway, as both are able to drastically inhibit Gli1 protein expression in murine NIH3T3 cells and in human melanoma cells without significant effect on a panel of 46 kinases." (PMID 29396391, 2018).
melanoma (continued). "In conclusion, in this study we provide evidence of a novel mechanism of non-canonical SMO-independent activation of GLI1 by the SOX2-BRD4 axis and describe the efficacy of a combinatorial treatment with a novel SMO inhibitor and the PROTAC-derived BRD4 degrader MZ1 in melanoma." (PMID 33958721, 2021).
gastric cancer (83 papers, 2007 to 2025). A primary or metastatic malignant neoplasm involving the stomach. "For gastric cancer in the TCGA database, high GLI1 expression was significantly associated with clinical stage and lymph node status." (PMID 40255562, 2025). "Taken together, we found that the GLI1 expression level is highly associated with chemosensitivity in gastric cancer cells." (PMID 28404967, 2017). "In fact, GLI1 protein was shown to be associated with the promoter fragment of ABCG2 through a Gli-binding consensus site in gastric cancer cells." (PMID 28404967, 2017). "More importantly, we have shown that higher GLI1/ ABCG2 expression is associated with poor survival of gastric cancer patients who underwent CDDP-based chemotherapy." (PMID 28404967, 2017). "Three studies including 316 patients were assessed for the correlation between Gli-1 and 5-year OS, which indicated that positive Gli-1 expression was associated with poor prognosis in gastric cancer patients (HR 2.14, 95%CI 1.35-3.40; P = 0.001)." (PMID 27634907, 2016). "Most studies confirm that high CD44, Shh, and Gli1 expression is significantly associated with poorer clinicopathological parameters and worse overall survival in gastric cancer." (PMID 26839535, 2016). "In accordance with these results, univariate Cox regression analysis also revealed that CD44, Shh, and Gli1 status were associated with the prognosis of gastric cancer in our study." (PMID 26839535, 2016). "The result indicated that positive Gli-1 expression was associated with poor prognosis in gastric cancer patients (HR 2.14, 95%CI 1.35-3.40; P = 0.001)." (PMID 27634907, 2016). "To assess the aggressiveness of CD44, Shh, and Gli1 for gastric cancer, we established biomarker risk score system to evaluate the prognostic importance." (PMID 26839535, 2016). "Given the facts that LATS1 is a critical regulator of YAP1 5 and YAP1 can upregulate Gli1 expression in esophageal squamous cell carcinoma 30 and gastric cancer 31, we speculated that YAP1 might be implicated in LATS1-mediated Gli1 suppression." (PMID 35003351, 2021). "We accessed whether the expression level of Gli1 or HER2 is associated with clinicopathological factors of postoperative gastric cancer patients." (PMID 29321573, 2018). "Targeting GLI1 G4 structures with alpha-estradiol and (R)-(-)-ibuprofen effectively inhibits gastric cancer progression by blocking GLI1/PRKACB signaling." (PMID 40255562, 2025). "Relevant researches reported that high GLI1 level also predicted poor prognosis in malignant mesothelioma 31, gastric cancer 32, hepatocellular carcinoma 33, and other cancer types." (PMID 41323789, 2025). "This study explores G4 stabilization in the GLI1 promoter as a novel strategy to suppress gastric cancer progression." (PMID 40255562, 2025). "Our study showed that PRKACB is highly expressed in gastric cancer and acts as a downstream regulator of GLI1 to promote gastric cancer progression." (PMID 40255562, 2025). "Our results have showed that G-quadruplex regulators on the GLI1 promoter inhibited gastric cancer progression by downregulating PRKACB, an effector molecule downstream of GLI1." (PMID 40255562, 2025). "Inhibition of GLI-1 expression reduced the expression of these markers in gastric cancer cells, suggesting an essential role for GLI-1 in colorectal cancer." (PMID 40224487, 2025). "Here, we studied the effects of G-quadruplex regulators of the GLI1 promoter on gastric cancer progression." (PMID 40255562, 2025). "Our study showed that GLI1 was overexpressed in gastric cancer tissue samples and that its expression was correlated with adverse clinicopathological parameters, suggesting a role for GLI1 in gastric carcinogenesis, progression, and metastasis." (PMID 40255562, 2025). "Attempting to block or silence the expression of GLI1 will significantly help suppress gastric cancer progression." (PMID 40255562, 2025).
gastric cancer (continued). "Alpha-estradiol and (R)-(-)-ibuprofen suppressed GLI1 transcription and protein levels, significantly inhibiting gastric cancer cell proliferation, migration, invasion, and stemness." (PMID 40255562, 2025). "In this study, a G-quadruplex was used as a target for inhibitor exploration, and a GLI1 molecule inhibitor was used as an entry point to verify the relationship between its aberrant activation and gastric cancer progression." (PMID 40255562, 2025). "GLI1 expression significantly increased in gastric cancer, kidney renal clear cell carcinoma and hepatocellular carcinoma and we selected GC for our study." (PMID 40255562, 2025). "In this project, we combined previous studies with the current research status and used the GLI1 molecule in the Hh pathway as a regulatory molecule to develop inhibitors for G-quadruplexes, providing a new option for the treatment of gastric cancer." (PMID 40255562, 2025). "MT1M suppression is known to promote cell growth and stemness properties in gastric cancer cell lines through increased GLI1 expression." (PMID 38751776, 2024). "Shh-Gli1 signaling was activated in CD44+ gastric cancer stem cells, which was responsible for drug resistance in advanced GC." (PMID 37596267, 2023). "Positive expression of GLI family zinc finger 1 (GLI1) has been recognized as a reliable indicator of poor prognosis in patients with highly aggressive gastric cancer." (PMID 36289675, 2022). "Further research revealed that miR-378a-3p inhibits GLI1/2 in the Hedgehog signaling pathway and attenuates the stemness of gastric cancer stem cells." (PMID 36245214, 2022). "For instance, previous research demonstrated that genistein suppresses Gli1 pathway in reversing CSC features in gastric cancer." (PMID 34769099, 2021). "SOX2, in addition to being transcriptionally regulated by Gli1, is post-transcriptionally regulated in gastric cancer by AKT activation in a ubiquitin-dependent manner." (PMID 33499351, 2021). "The miR-30c-2-3p acts on RAB31 and regulates the GLI1 signaling pathway in gastric cancer tumorigenesis and development." (PMID 34067819, 2021). "Immunohistochemical analysis of gastric cancer tissues revealed a significant correlation of Gal1 and GLI1 expression, and GLI1 expression was significantly correlated with VM." (PMID 34572373, 2021). "In this study, the GLI1-targeted siRNA nanoparticles selectively eliminated gastric CSCs for dual-targeting CD44 and GLI1, and consequently exhibited impressive therapeutic efficacy in gastric cancer." (PMID 34959397, 2021). "For instance, the overexpression of β-catenin reduced butyrate-induced GLI1 overexpression in gastric cancer cells, making their crosstalk in cancers more perplexing than it seems." (PMID 34572373, 2021). "Lentiviruses packaged with this plasmid and appropriate guide RNAs (gRNAs) successfully knocked out the genes RhoA, Gli1, and Gal3 in human gastric cancer cell lines." (PMID 32053639, 2020). "The over-expression of GLI1 is a credible indicator of poorer prognosis for a variety of cancers including gastric cancer and esophageal squamous cell carcinoma (ESCC)." (PMID 32913560, 2020). "PRMT5-mediated GLI1 stabilization machinery has also been observed in the previously identified SHH-expressing gastric cancer cell line AGS and the small-cell lung cancer (SCLC) cell line H146." (PMID 32859041, 2020). "Our previous study indicates that Rab1A expression is closely related to GLI1 expression in gastric cancer." (PMID 33214609, 2020). "Studies in SHH-expressing gastric cancer cells and small cell lung cancer showed that GLI1 is methylated at three Arginine residues (515, 990 and 1018) by the methylosome protein 50 (MEP50)/PRMT5 complex." (PMID 31244888, 2019). "Results showed decreased GLI1 phosphorylation in the shIntegrin β3#1 group compared to the blank control in BGC-823 MCA cells.These results indicated that Integrin αvβ3 can specifically regulate GLI1 in gastric cancer MCAs." (PMID 31366904, 2019).